AIM2 (absent in melanoma 2)
Diseases named in the same sentence as AIM2 in open-access papers (continued):
Sharing a sentence is not in itself a finding about the gene and the disease.
tumor (continued). "The spatial and temporal activation and expression of AIM2 and NLRP3 in varying tumor types may explain the conflicting reports but more studies are needed to fully understand the importance of the inflammasomes and its components in cancer." (PMID 37449203, 2023). "In addition, AIM2 inhibited Gli1 expression through the smoothened homolog (SMO)‐independent pathway and regulated tumor cell proliferation and migration in a Gli1‐dependent manner." (PMID 36161280, 2023). "Consequently, patients with higher AIM2 expression had a higher TMB and more neoantigens, thereby improving the likelihood of tumor cells being eliminated by T cells." (PMID 37932362, 2023). "We showed that deletion of NLRP3, but not AIM2, phenocopied caspase-1/IL-1β dependent tumor progression in vivo." (PMID 36439171, 2022). "Furthermore, not all the transcripts associated with the inflammasome complex were enriched in the tumor, such as IL18, AIM2, PYCARD, and GSDMD." (PMID 36439171, 2022). "In contrast, a decrease in tumor growth in cutaneous squamous cell carcinoma is observed in the absence of AIM2." (PMID 35734577, 2022). "Our results highlight that activation of the AIM2 inflammasome in BLCA cells, as that in immune cells, could mediate the anti-tumor activities." (PMID 36386141, 2022). "In these tumor tissue, most pyroptosis-related molecules, particularly IRF1, GZMB, CASP5, BAK1 and AIM2, were consistently inhibited in the cell cycle, DNA damage response, hormone AR and RTK signaling pathway, but highly activated in the apoptosis signaling way." (PMID 36437960, 2022). "We found that tumor growth was blunted in NLRP3 null mice, which phenocopied the previously demonstrated protective effect found in caspase-1 null mice but was unaltered in AIM2 null mice." (PMID 36439171, 2022). "Furthermore, the AIM2 inflammasome elicits immunosuppression following antibody-dependent cell phagocytosis (ADCP) and tumor cell DNA sensing, by upregulating PD-L1 and IDO expression, which inhibit anti-tumor immunity by NK and T cells." (PMID 35517498, 2022). "Furthermore, AIM2, CASP4, GSDMB, NOD2, and RBCK1 were also found to be highly expressed in ccRCC cell lines and tumor tissues, and GASP4 and GSDMB promote ccRCC cells’ proliferation, migration, and invasion." (PMID 36248876, 2022). "At the same time, the heatmap showed that AIM2, GSDMB and GSDMC were overexpressed in tumor group." (PMID 36034461, 2022). "By elegant step-by-step approaches, the authors demonstrated that TTFields promote the production of immune-stimulating proinflammatory and interferon type 1 cytokines in tumor cells in a cGAS/STING- and AIM2 inflammasome–dependent mechanism, thereby activating the immune system." (PMID 35426370, 2022). "KIRC cells had the lowest AIM2 inflammasomes score, suggesting that the AIM2 inflammasomes reflect the tumor microenvironment rather than the tumor itself." (PMID 36248785, 2022). "In view of the fact that it is not clear whether lymph node metastasis occurs in many patients with KIRC, it was impossible to clearly show the effect of the expression of AIM2 and DFNB59 on the lymph node metastasis of tumor cells." (PMID 35281845, 2022). "Next, we conducted Western blot analysis to assess the protein expression of AIM2 across four pairs of GC tumor tissues, and adjacent non-tumorous tissues." (PMID 33859277, 2021). "Our results indicated that cleaved IL-1β and IL-18 were extremely low, regardless of the expression level of AIM2 in tumor cells." (PMID 33391539, 2021). "In addition, the results of immunohistochemistry showed that AIM2, as well as the cell proliferation marker Proliferating Cell Nuclear Antigen (PCNA) in tumor tissues were significantly downregulated by luteolin." (PMID 30833546, 2019). "Mechanistically, these pseudoviruses activate the NLRP3 and AIM2 inflammasomes, leading to caspase-1-mediated tumour regression that is dependent on neither cytotoxic T lymphocytes nor humoral immune response." (PMID 28397782, 2017).
tumor (continued). "It is recently recognized that AIM2 plays an important dual role in both innate immunity and tumor pathology, though its role in cancer is not fully clarified." (PMID 27167192, 2016). "It indicated that lack of AIM2 expression endowed tumor cells proliferative and invasive capabilities, which further render cancer cells more aggressive and prone to metastasis." (PMID 27167192, 2016). "Thus, overexpression of AIM2, RIG-I and NLRP3 inflammasomes and IL-1β in tumour cells likely contributes to local tumour control." (PMID 23065753, 2012). "We found that 25 out of the 33 tested inflammasome-related genes were detectable by quantitative RT-PCR, and 8 of them (CIITA, NLRC4, NLRP3, NLRP7, AIM2, RIG-I, ASC and IL-1β) were overexpressed (fold change, >2) in NPC tumour samples, compared to adjacent normal samples." (PMID 23065753, 2012). "None of the patients whose tumours showed upregulation of AIM2 or NLRP3 inflammasomes had local recurrence within 5 years after treatment." (PMID 23065753, 2012). "AIM2 has been shown to impede the malignant behaviors of CRC cells, such as proliferation and migration, through modulation of the AKT/mTOR signaling pathway, NF-κB signaling pathway, Notch signaling pathway, mitochondrial dynamics, and cell cycle regulation, thereby exhibiting anti-tumor effects." (PMID 39744568, 2025). "Although these studies demonstrated that periodontal pathogens can modulate NLRP3 expression in vitro and in vivo mouse models, they did not explore the role of AIM2 in tumour growth in vivo or examine AIM2 activation in response to bacteria-induced DNA damage." (PMID 41440367, 2025). "Therefore, AIM2 may represent a valuable prognostic marker and therapeutic target in SCC, warranting further investigation into its role in tumor progression and metastasis." (PMID 40386782, 2025). "Considering the complex nature of tumor growth and the obvious biological diversity between cancer types, it is not surprising that the AIM2 inflammasome could exert both a tumor-promoting or a tumor-suppressive role." (PMID 40002808, 2025). "Besides, AIM2 overexpression also could downregulate expression of M2 markers (Arg‐1 and YM1) in the tumor tissues." (PMID 39222064, 2024). "Whereas this effect was mostly dependent on NLRP3, not Aim2, inflammasome, since knockout of Nlrp3, Asc, or caspase‐1 but not Aim2 through CRISPR‐Cas9 technique in DC2.4 cells markedly decreased the protein level of IL‐1β induced by the Arf1‐ablated tumor cells." (PMID 37786300, 2023). "It indicated that AIM2 might not rely on the anti-tumor inflammatory cytokines to affect immune response in PSCC cells." (PMID 33391539, 2021). "Besides, the result of in vivo experiment demonstrated that the restoration of AIM2 expression could inhibit the tumor progression of BRAF-mutant CRC, including tumor growth and distant metastasis." (PMID 33842454, 2021). "We showed that lack of AIM2 expression in HCC tissues was significantly correlated with larger tumor volumes, lower differentiation status, more advanced disease stages and more metastasis, which indicated that loss of AIM2 expression in HCC patients contributed to disease progression." (PMID 27167192, 2016). "Furthermore, IF staining of tumor tissues in the combination therapy group revealed that CD8+ T cell infiltration was higher in tissues with elevated expression of DNASE1L3 and AIM2, whereas the knockdown of AIM2 led to a significant reduction in CD8+ T cell numbers." (PMID 39479454, 2024). "Notably, this study did not elucidate whether the AIM2 inflammasome contributes to these pro-tumor effects." (PMID 39600708, 2024). "High expression of AIM2 may not promote lymph node metastasis of tumor." (PMID 35281845, 2022). "However, the xenograft could not be eliminated totally only by Ad‐CAIXpromotor‐AIM2, which might be due to immune escape from the tumour, such as the expression of PD‐L1 inhibitory signals or immunosuppressive cells." (PMID 32725966, 2020).
tumor (continued). "The results revealed that silencing AIM2, RIG-I, or MDA-5 did not significantly reduce IFN-β secretion from the “BC@Z-M + L”-treated 4T1 tumor cells as well as their capacity to trigger BMDC maturation." (PMID 39613774, 2024). "While we did not see a role for the DNA sensing molecule AIM2 in our studies, others have noted a myeloid-intrinsic STING-dependent mechanism to render the tumor more responsive to immune checkpoint inhibitors." (PMID 36439171, 2022). "Our microarray data and RT-qPCR results revealed that other pattern recognition receptors, such as AIM2 and RIG-I, also showed elevated expression in OSCC tumor tissues (data not shown)." (PMID 27367024, 2016). "This group includes interferon-inducible protein 16 (IFI16), myeloid cell nuclear differentiation antigen (MNDA), absent in melanoma 2 (AIM2), and pyrin and HIN domain family member 1 (PYHIN1), each of which has been reported to be related to tumor progression." (PMID 37998338, 2023). "For example, inflammasome components such as Absent in melanoma 2 (AIM2) has been demonstrated to be aberrantly expressed in NSCLC, and its overexpression could lead to tumor growth." (PMID 35884843, 2022). "This subsequently triggers absent in melanoma 2 (AIM2)/caspase‐1/gasdermin D (GSDMD)‐mediated pyroptosis, thereby enhancing tumor immunity and the efficacy of anti‐PD‐L1 immunotherapy in both microsatellite instable (MSI) and microsatellite stable (MSS) tumor cells." (PMID 39903759, 2025). "Although the validation of the contribution of AIM2 expressed in immune/mesenchymal cells in PSCC has not been investigated, the preliminary results might provide valuable insights into the important role of tumor progression." (PMID 33391539, 2021).
infection (184 papers, 2011 to 2026). The state of being infected such as from the introduction of a foreign agent such as serum, vaccine, antigenic substance or organism. "In accordance with the resistance observed in Aim2−/− mice towards C. albicans infection, AIM2 deficiency results in a reduction of inflammation levels subsequent to infection." (PMID 38918243, 2024). "For example, AIM2 activation in DCs is essential for controlling infections caused by pathogens such as Francisella novicida, Mycobacterial species and Adenovirus." (PMID 39076969, 2024). "They detected increased susceptibility of Aim2-/- mice to intratracheal infection, which they related to decreased caspase-1 cleavage as well as lower IL-1β and IL-18 levels in the lungs." (PMID 39324136, 2024). "AIM2 activation in monocytes contributes to T cell death following tissue injuries, increasing susceptibility to life-threatening infections." (PMID 39076969, 2024). "Recognition of M. tb DNA by AIM2 initiates the activation of the AIM2 inflammasome, a multiprotein complex involved in triggering pyroptosis, a type of cell death that promotes inflammation and aids in clearing the infection caused by M. tb." (PMID 39125766, 2024). "Substantiation for this can be found in studies on AIM2-deficient models, revealing enhanced susceptibility to intratracheal infection with Mycobacterium tuberculosis." (PMID 38029270, 2023). "To this end, we infected WT, Gbp1–/–, Gbp2–/–, Gbp3–/–, Gbp5–/–, and Aim2–/– mice with F. novicida and monitored their susceptibility to infection." (PMID 35906252, 2022). "AIM2-deficient mice infected with Mycobacterium bovis Bacillus Calmette-Guérin (BCG) showed a higher infection burden and developed severe disease due to simultaneous induction of reactive IFN-β and IFN-γ responses compared to wild-type mice." (PMID 33868225, 2021). "Macrophages from AIM2-deficient mice were highly susceptible to intratracheal infection with Mtb, and this deficiency resulted in severe inhibition of the AIM2 inflammasome, associated with defective IL1 and IL18 production and impaired Th1 responses." (PMID 32373118, 2020). "The impact of AIM2 deficiency in the secretion of IL-1β by macrophages infected with isolate 4I2 was more pronounced than that seen in the case of infection with 6C4." (PMID 32327653, 2020). "To address this issue, we isolated pDCs from YM-infected WT and gene deficient (Aim2−/−, Nlrp3−/−, Casp1−/−, Il1r1−/−, and Mavs−/−) mice at 18 h post YM infection and assessed mRNA expression levels of SOCS1, IFN-α and IFN-β." (PMID 30470758, 2018). "IOE-infected AIM2-/- mice were susceptible to infection with 100% of the AIM2-/- mice died on day 8–10 p.i. similar to WT mice." (PMID 29049365, 2017). "After Ft LVS infection IL-1β and IL-18 levels are similar between Aim2- and Nlrp3-deficient mice, yet mice deficient in Aim2, ASC, or caspase-1/11 do not reproduce the survival phenotype of Nlrp3 mice." (PMID 27926940, 2016). "Like BMDMs, BMDCs derived from ASC-, AIM2-, or caspase-1-deficient mice are defective for cell death, IL-1β secretion and caspase-1 processing in response to infection with wildtype F. novicida." (PMID 25879288, 2015). "The importance of the AIM2 inflammasome upon PAMP recognition has been confirmed by infection experiments using aim2-deficient macrophages infected with Francisella tularensis, L. monocytogenes, vaccinia virus, herpes simplex virus-1 and mouse cytomegalovirus." (PMID 23316484, 2012). "Therefore, it has been suggested that AIM2 is associated with inflammation caused by partial viral invasion infections." (PMID 37608944, 2023). "Furthermore, loss of caspase‐1 protein during Tg infection contributed to the switch in AIM2‐dependent pyroptosis to apoptosis." (PMID 31268602, 2019). "Similarly, mice deficient in AIM2 are highly susceptible to the intratracheal infection with Mycobacterium tuberculosis." (PMID 30456207, 2018).
infection (continued). "Because the AIM2 inflammasome plays an important role in the host defense against infection, we investigated whether the association between pUL83 and AIM2 affects the subsequent assembly of the inflammasome and IL-1β activation." (PMID 28219398, 2017). "Indeed, Caspase-1/11- and Aim2-deficiency is associated with ineffective clearance of Ft, as evidenced by bacterial burdens comparable or higher than control mice later in infection." (PMID 27926940, 2016). "Given the two pathways that are associated with cytosolic dsDNA, we hypothesized that the AIM2 inflammasome activation takes part in inducing autophagy during infection with M.bovis." (PMID 27409673, 2016). "However, following lethal infection with Francisella, IL-1r-, Caspase-1/11-, Asc- and Aim2-deficient mice exhibited increased susceptibility as expected, while Nlrp3-deficient mice were more resistant." (PMID 27926940, 2016). "Notably, AIM2 can also sense infections caused by RNA viruses." (PMID 41062723, 2025). "The suppression of AIM2 inflammasome activation could represent a pivotal element in the virulence of Mtb, given that mice lacking AIM2 (−/−) have exhibited a heightened susceptibility to infection." (PMID 39456188, 2024). "Therefore, IL-1β may be involved in the signaling cascade activated by AIM2 inflammasome, causing immune suppression and secondary infection after stroke injury." (PMID 35173738, 2022). "Recently, it has been reported that the AIM2 inflammasome-derived IL-1β production activated triggers the expression of FasL in the spleen monocytes which evokes the apoptosis of Fas-dependent extrinsic T cells, causing an increased risk of infection by bacteria after ischemic stroke." (PMID 35173738, 2022). "Furthermore, GSDMD-independent secondary necrosis appears to contribute to the clearance of bacterial infection, as it could be shown that Gsdmd−/− mice are less susceptible to infection with Francisella novicida compared with Casp1- or Aim2-deficient animals." (PMID 32345661, 2020). "The PYHIN (pyrin and HIN domain-containing) gene family encodes central cytosolic DNA sensors, including AIM2 and IFI16, that activate inflammasome and type I interferon pathways during infection." (PMID 42292384, 2026). "IRF1 also regulates the expression of key components necessary for NLRP3 and AIM2 activation after infection, including ZBP1 and guanylate-binding proteins." (PMID 40018047, 2025). "More importantly, CAST/EiJ mice succumbed to MPXV infection within 8 days; however, AIM2 inhibition significantly prolonged survival, with 10% of treated mice surviving the infection." (PMID 41225161, 2025). "AIM2 cooperates with CASP1 and ASC to form the AIM2 inflammasome, which recognizes infection by pathogenic microorganisms and binds to cytoplasmic double-stranded DNA to initiate the innate immune response and induce inflammation." (PMID 40625798, 2025). "The AIM2/ASC complex activated caspase-8-mediated cell death in caspase-1 knockout macrophages upon infection with intracellular bacteria, Francisella novicida." (PMID 40006996, 2025). "Similar to microglia and monocytes/macrophages, the Dendritic 1 cluster in Rag1–/– mice had significant reductions in Type I and Type II IFN responses, IL-1 production, AIM2 inflammasome, and Ag presentation pathways primarily at day 7 after infection." (PMID 39989461, 2025). "Both pyroptosis and caspase-3-mediated apoptosis are also known to occur during infection with Francisella tularensis when host AIM2 recognizes double-stranded DNA in the cytosol." (PMID 39772728, 2025). "During pathogen infection, AIM2 interacts with ZBP1 and Pyrin to form the AIM2-PANoptosome, thereby triggering PANoptosis." (PMID 41479920, 2025). "Age- and sex-matched cohorts of 6–8-week-old WT and Aim2–/– mice (C57BL/6J background) or CAST/EiJ mice cohoused under identical conditions were used for the MPXV infection experiments." (PMID 41225161, 2025).